NLRP3 (NLR family pyrin domain containing 3)
Diseases named in the same sentence as NLRP3 in open-access papers (continued):
Sharing a sentence is not in itself a finding about the gene and the disease.
asthma (continued). "In this study, we demonstrate that HDM challenge induced NLRP3 inflammasome activation in alveolar macrophages in the airway, which promoted lung inflammation and tissue damage in asthma." (PMID 34413860, 2021). "This is especially interesting in chronic inflammatory skin and allergic diseases that reportedly are stress-sensitive and involve NLRP3 inflammasome activation such as psoriasis, contact hypersensitivity or asthma." (PMID 33815383, 2021). "It has been demonstrated that the expression of NLRP3, caspase-1 and IL-1β is enhanced in the lungs of asthma patients and allergen-induced asthmatic mice compared to healthy controls." (PMID 34413860, 2021). "While NLRP3 inflammasome has been initially recognized to provide protective immunity by facilitating the clearance of pathogens in the airways, over-activation of NLRP3 inflammasome can lead to the exacerbation of airway inflammation and asthma." (PMID 34868022, 2021). "Although the involvement of NLRP3 inflammasome in asthma pathogenesis has been widely reported, such an allergic inflammatory response is mainly triggered by the TLR-pathways in murine models and humans." (PMID 33546184, 2021). "Growing evidence has suggested a major role for NLRP3 inflammasome activation in the development of airway inflammation and exacerbation of asthma features." (PMID 34868022, 2021). "The NLRP3 inflammasome is a critical component of innate immunity and contributes to the pathology of human diseases, such as asthma, COPD, and pulmonary inflammation." (PMID 33419073, 2021). "Recent studies have reported that the NLRP3 inflammasome plays an important role in directing Th1/Th17 responses in neutrophil-dominant severe asthma and several other inflammatory diseases that involve neutrophilic response." (PMID 34064821, 2021). "miR‐223 was participated in the regulation of neutrophilic airway inflammation through inhibiting the activation of NLRP3/IL‐1β signaling pathway in the asthma model." (PMID 33332758, 2021). "In an OVA-induced asthma model, allergen inhalation induced ROS production, NLRP3 inflammasome components expression and inflammasome assembly in mouse bronchial epithelial cells." (PMID 34413860, 2021). "We identified the NLRP3 inflammasome as an important regulator in the development of asthma and identified an inhibitor targeting NLRP3 that is effective for treating HDM-induced allergic asthma." (PMID 34413860, 2021). "Exposure to gastric bacteria H. pylori can also drive asthma protection by inducing IL-18 in dendritic cells through the NLRP3/CASP1/IL-18 axis." (PMID 33546184, 2021). "NLRP3 can act as a transcriptional regulator to induce the differentiation of TH2 cells to promote asthma symptoms in an inflammasome-independent manner." (PMID 34413860, 2021). "Collectively, these results show that NLRP3 is required for the promotion of TH2 responses and the pathological damage caused by asthma." (PMID 34413860, 2021). "Upregulation miR-223 can inhibit the airway inflammation and pro-inflammatory cytokines production through inhibiting the activation of NLRP3/IL-1β signaling pathway in mice, which is involved in the pathogenesis of asthma." (PMID 32423405, 2020). "In a previous study, the NLRP3 inflammasome was shown to regulate M2 polarization via the upregulation of IL-4 in asthma." (PMID 33182702, 2020). "This indicates that IL-1β and NLRP3 play an important role in neutrophilic asthma inflammation and in COPD." (PMID 32509795, 2020). "Toll-like receptor 2 (TLR2) is suggested to initiate the activation of NLRP3 inflammasome, and considered to be involved in asthma." (PMID 32117301, 2020). "This was in agreement with other studies showing that blockade of NLRP3 inhibited both eosinophilic and neutrophilic inflammation in severe asthma." (PMID 32423405, 2020). "NLRP3 inflammasome plays a pivotal role in pulmonary inflammation related diseases (chronic obstructive pulmonary disease, asthma, and ARDS)." (PMID 32765942, 2020).
asthma (continued). "Particularly, as the best-characterized subtype shown to be expressed in airway, nucleotide-binding domain and leucine-rich repeat protein 3 (NLRP3) inflammasome is considered to be involved in the progress of asthma." (PMID 32117301, 2020). "NLRP3 inflammasome is one of the most extensively characterized NLRs due to its relevance in human inflammatory disorders such as asthma." (PMID 32117301, 2020). "The NLRP3 inflammasome plays a pivotal role in pulmonary inflammation related diseases as chronic obstructive pulmonary disease, asthma, and ARDS." (PMID 32765942, 2020). "In summary, a growing body of evidence suggests that NLRP3-induced inflammasome responses are implicated in AAI both in experimental models and human asthma." (PMID 31590215, 2019). "Over the past few decades, growing evidence has indicated that the inflammasome nucleotide-binding oligomerization domain, leucine-rich repeat and pyrin protein containing 3 (NLRP3) plays a critical role in airway inflammations, such as asthma." (PMID 30373775, 2019). "In fact, the direct comparison of the expression and activation of NLRP3 in mouse models and patients with distinct asthma severities is essential for the identification of novel biomarkers pertinent to the diverse asthma endotypes." (PMID 31590215, 2019). "Other studies have shown NLRP3 activation following allergen exposure enhanced N6-etheno- ATP (eATP) in bronchoalveolar lavage (BAL) fluid resulting in an elevation of IL-1β in asthma." (PMID 30447690, 2018). "Several studies have revealed that NLRP3 inflammasome activation is involved in the pathogenesis of asthma." (PMID 30363922, 2018). "In the present study, we investigated vitamin D3 levels, airway hyper-responsiveness, cytokine levels, and NLRP3 and IL-1β mRNA expressions by developing a mouse model of obese asthma via OVA-challenge and high-fat diet." (PMID 29160418, 2017). "Obese asthma mice showed a significant increase in airway hyper-responsiveness, airway inflammation, pro-inflammatory cytokine levels and NLRP3 mRNA, IL-1β mRNA expression." (PMID 29160418, 2017). "Two recent reviews detail the importance of the NLRP3 and related inflammasomes in acute lung injury and chronic inflammatory lung diseases including asthma and COPD." (PMID 27650313, 2016). "Here, we examined the anti-asthma effect of Andrographolide and provided the data which showed that Andrographolide significantly reduced NF-κB and NLRP3 inflammasome activation and finally alleviated the symptoms in OVA-treated mice." (PMID 27793052, 2016). "Immunohistochemical localization and induction of NLRP3 inflammasome were also demonstrated in an ovalbumin-induced asthma model." (PMID 24671176, 2014). "It examines how analyzing sputum provides important insights into the degree of airway inflammation, the relationship between NLRP3 expression and asthma severity, and its potential as a biomarker for monitoring disease progression and response to therapy in children." (PMID 41318536, 2025). "More research is required and essential to confirm that NLRP3 could be used as a biomarker or therapeutic target in pediatric asthma." (PMID 41318536, 2025). "Researchers have proposed that targeting the NLRP3 inflammasome may provide new treatment options for asthma management, specifically allergic asthma." (PMID 40851698, 2025). "Understanding of the relationship between NLRP3 inflammasome activity and pediatric asthma pathobiology may help in the development of novel, targeted therapeutic strategies for children." (PMID 41318536, 2025). "This less-invasive approach could greatly enhance phenotyping accuracy in pediatric NLRP3-related asthma studies when sputum collection proves difficult." (PMID 41318536, 2025). "In adults with asthma, airway tissues and immune cells from patients, especially those with severe or steroid-resistant phenotypes, have been reported to have larger amounts of the NLRP3 inflammasome and to be more active." (PMID 41318536, 2025).
asthma (continued). "In this model, elevated NLRP3 and IL-1 correlated with poorer asthma control and lower FEV1 values." (PMID 41318536, 2025). "This role highlights NLRP3 as an essential factor in epithelial homeostasis and underscores its potential as a therapeutic target for interventions to improve barrier integrity in respiratory diseases, such as asthma." (PMID 41394833, 2025). "Mefenamic acid could play a dual role in managing asthma in children through its antagonistic effects on bradykinin and inhibition of the NLRP3 inflammasome." (PMID 40851698, 2025). "Additionally, NLRP3 overexpression experiments were conducted to elucidate the molecular mechanism by which KIF1B mediates inflammatory pathways in asthma pathogenesis." (PMID 41384344, 2025). "Research indicates that the NLRP3 inflammasome is critical in driving the pathogenesis of asthma." (PMID 40832584, 2025). "The HMGB1/NLRP3 axis plays a pivotal role in asthma initiation and progression." (PMID 40688353, 2025). "Orosomucoid-like protein 3 (Ormdl3) gene which is associated with asthma have been found to alter sphingolipid levels including CER, and augmented the expression of pyroptotic markers such as NLRP3 and GSDM-D in lung tissues of obese asthmatic mice and human bronchial epithelial cells." (PMID 41335598, 2025). "According to recently published data, which suggests that activation of NLRP3 inflammasome may influence asthma severity, phenotype heterogeneity, and treatment resistance, especially in neutrophilic or corticosteroid-resistant pediatric asthma." (PMID 41318536, 2025). "The expression of NLRP3 was elevated in the lung tissues in asthma mice." (PMID 40343297, 2025). "Additionally, NLRP3 (NLR family pyrin domain containing 3) inflammasome activation has been shown to drive severe asthma through the regulation of IL‐1β and IL‐18 cytokine levels." (PMID 41384344, 2025). "To determine whether TVE treatment inhibits the NLRP3 inflammasome in vivo, we used asthma mouse models." (PMID 38668995, 2024). "Moreover, studies have shown that particulate matter, such as silica nanoparticles, can exacerbate airway inflammation in mouse models of asthma by activating NLRP3 inflammasomes." (PMID 39131161, 2024). "The observed effects correlated with reduced expression levels of nucleotide-binding oligomerization domain (NOD)-like receptor containing pyrin domain 3 (NLRP3) inflammasome components in the primary airway epithelial cells of mice with house dust mite (HDM)-induced asthma." (PMID 39834584, 2024). "Neutrophilic asthma (NA) is a severe form of asthma with no known cure, and abnormal activation of the NLRP3 inflammasome is implicated in the development of NA." (PMID 38668995, 2024). "Thus, the role of NLRP3/caspase-1 signaling in asthma appears to depend on the inflammatory phenotype of asthma." (PMID 39611173, 2024). "Caspase-1- or NLRP3-deficient mice exposed to HDM exhibited enhanced eosinophil recruitment, and exacerbated airway inflammation, suggesting that the NLPR3/caspase-1 axis restrain eosinophilic inflammation in asthma." (PMID 39611173, 2024). "There is increasing evidence that NLRP3 inflammasome plays a role in asthma." (PMID 38177104, 2024). "Numerous studies implicate NLRP3 inflammasomes, IL-1β and IL-18 in the development of asthma." (PMID 39131161, 2024). "Consequently, targeting NLRP3 inflammasome when aiming at IL‐1β as a therapeutic target for severe asthma has proven to be effective." (PMID 38668995, 2024). "In recent years, some research hot words such as “severe asthma,” “innate lymphoid cells,” “thymic stromal lymphopoietin,” “NF-κB,” “airway remodeling” and “NLRP3 inflammasome” have emerged, and a large number of articles have conducted in-depth research on them." (PMID 39029036, 2024). "Similarly, NLRP3 inhibition attenuated bronchial inflammation and hyperresponsiveness in asthma mouse models induced by house dust mite (HDM) or toluene diisocyanate (TDI)." (PMID 39611173, 2024).
asthma (continued). "Similarly, miR-20b targets the TXNIP, suppresses TXNIP expression, and reduces TXNIP binding to NLRP3, thereby limiting pyroptosis and airway inflammation in a murine model of asthma." (PMID 39131161, 2024). "The levels of IL-1β in sputum and bronchoalveolar lavage fluid were higher in patients with asthma than in normal healthy adults, suggesting that the NLRP3 inflammasome may be involved in respiratory inflammation." (PMID 38945951, 2024). "We speculate that the possible mechanism is that there are a large number of endogenous ' danger signals ' that can activate NLRP3 inflammasome in the airway of mice during acute asthma attacks." (PMID 38117410, 2024). "Additionally, studies have shown that expression levels of key downstream indicators of the NLRP3 pathway (interleukin [IL]-1β and IL-18) were significantly elevated in the peripheral blood of patients with asthma." (PMID 39834584, 2024). "In addition, the protein expression levels of NLRP3, caspase-1, cleaved caspase-1, GSDMD, GSDMD-N, IL-18, and IL-1β were increased, indicating that MUC1, TLR4/MyD88/NF-κB pathway, and NLRP3-induced pyroptosis are involved in the pathogenesis of asthma." (PMID 37880668, 2023). "The mRNA expressions of TLR4, MyD88, nucleotide-binding oligomerization domain-like pyrin domain-containing protein 3 (NLRP3), caspase-1, interleukin (IL)-18, and IL-1β in induced sputum cells of patients with asthma were upregulated and related to the mRNA expression of MUC1." (PMID 37880668, 2023). "NLR family, pyrin domain containing 3 (NLRP3) inflammasome is a multimeric complex consisting of three parts NLRP3 receptor protein, pro‐caspase‐1, and apoptosis speck‐like protein and is implicated in airway inflammation in both COPD and asthma." (PMID 37904708, 2023). "Additionally, sputum expression of NLRP3 and IL-1β mRNA correlated with increased neutrophil numbers, severity of airflow obstruction and reduced disease control in these asthma patients." (PMID 37598239, 2023). "Moreover, NLRP3 inflammasome activation, which is critical in the pathogenesis of asthma, is triggered only in AMs from HDM-challenged mice, indicating that the activation of the NLRP3 inflammasome in the lungs of asthmatic mice is dependent on AMs." (PMID 36830047, 2023). "Here, we show that systemic immune cells from all patients with asthma, both severe and non-severe asthmatics that contain both eosinophilic and non-eosinophilic populations, have an increased ability for nigericin-induced NLRP3 inflammasome activation compared to those from non-asthma subjects." (PMID 38044426, 2023). "We next performed analyses to determine whether increased nigericin-induced NLRP3 inflammasome-mediated IL-1β release in asthma patients is different in males compared to females, or in obese compared to non-obese subjects." (PMID 38044426, 2023). "Furthermore, this study adds to the evidence that MUC1 regulates the TLR4/MyD88/NF-κB pathway and NLRP3 inflammasome-mediated pyroptosis in patients with asthma." (PMID 37880668, 2023). "Several previous studies have suggested that neutrophilic airway inflammation in asthma may be effectively reduced by blocking NLRP3 inflammasome-mediated pyroptosis; however, the results of clinical trials have been disappointing." (PMID 37880668, 2023). "Likewise, an involvement of NLRP3 inflammasome in HDM-models of asthma and in severe asthma in humans has been demonstrated, however data are conflicting and remain poorly understood." (PMID 37087523, 2023). "In addition, a preclinical model of OB and asthma showed a significant increase in airway hyper-responsiveness, airway inflammation, pro-inflammatory cytokine levels, mRNA expression of NLRP3 and IL1β in mice with OB, asthma, and lower 25(OH)D levels." (PMID 37867510, 2023). "The assembled NLRP3 inflammasome cleaves pro-Caspase-1 proteolysis into mature Caspase-1 to promote the release of the inflammatory factors IL-1β and IL-18, mediating immune imbalances in asthma." (PMID 38029078, 2023).
asthma (continued). "Furthermore, inhibition of NLRP3-mediated pyroptosis has been reported to ameliorate airway neutrophilic inflammation in a murine asthma model." (PMID 37880668, 2023). "Targeting the NLRP3 inflammasome is a potential strategy for treating asthma." (PMID 36903624, 2023). "Finally, we determined the effectiveness of MCC950 treatment in reducing NLRP3 inflammasome-mediated IL-1β release from PBMCs from patients with asthma." (PMID 38044426, 2023). "Furthermore, the gut microbiota exacerbated OVA-induced allergic asthma through the NLRP3/IL-1β signaling pathway in asthma model mice." (PMID 38029078, 2023). "Furthermore, we show that increased LPS + nigericin-induced NLRP3 inflammasome-mediated IL-1β release from PBMCs from patients with severe asthma correlate with increased total eosinophil and neutrophil numbers in the airways." (PMID 38044426, 2023). "Given this background, the NLRP3/caspase-1/IL-1β pathway apparently plays an important role in the pathogenesis of asthma, but the precise effects of NLRP3 inflammasome activation on airway inflammation in an OVA-induced murine model of neutrophilic asthma remain elusive and deserve investigation." (PMID 35664352, 2022). "Previous studies have highlighted the role of NLRP3 inflammasome in the pathogenesis of asthma." (PMID 35664352, 2022). "Thus, it is likely that the ROS-mediated autophagy/mitophagy or NLRP3 inflammasome plays an important role in vanadium co-exposure-induced allergic airway inflammation and asthma, which warrant a further investigation in the future." (PMID 36776398, 2022). "While further research is needed to pinpoint the exact mechanism, these results provide light on the etiology of neutrophilic asthma and indicate that blocking the NLRP3/caspase-1/IL-1 pathway might be a viable asthma treatment target." (PMID 35664352, 2022). "Several studies have demonstrated that NLRP3 plays an important role in asthma." (PMID 35187081, 2022). "Targeting the NLRP3 inflammasome is therefore also the key to the treatment of asthma." (PMID 35711428, 2022). "Moreover, among the various phenotypes of asthma, the expression of NLRP3, caspase-1, caspase-4, and other PRGs in neutrophil asthma significantly increases and NLRP3 inflammatory bodies can drive animal asthma models to produce glucocorticoid resistance." (PMID 35967302, 2022). "Accordingly, NLRP3/caspase-1/GSDMD-induced pyroptosis of BECs may be involved in the deterioration of asthma." (PMID 35819638, 2022). "Other miRNA’s that negatively regulate NLRP3 protein expression are miR-22-3p, miR-133b-3p, miR-186-5p, and miR-495-3p which have been studied in a variety of disease states including asthma, AD, allergic inflammation, cardiac microvascular endothelial cell injury (CMEC) and more." (PMID 35754962, 2022). "Given that NOX4 can regulate the expression of ROS, NOX4 may also be involved in regulating NLRP3 activation in asthma." (PMID 35711428, 2022). "Interestingly, NLRP3 inflammasome activation by chemical, pathogen, and allergen exposure is a key factor that drives various pulmonary diseases, including asthma, pulmonary fibrosis, and chronic obstructive pulmonary disease (COPD)." (PMID 36432032, 2022). "In addition, NLRP3 inflammasome activation is crucial in the pathogenesis of several pulmonary inflammatory diseases, including asthma." (PMID 36077310, 2022). "In the autophagy inhibition asthma model, NLRP3 induces monocyte activation." (PMID 35619697, 2022). "Similarly, mice with OVA-induced asthma showed a significantly higher expression of NLRP3, Caspase-1, IL-1β in lung tissues, and QF can significantly downregulate the expression levels of these proteins." (PMID 36081945, 2022). "In addition, some authors have provided data that implicates the NLRP3 response in Th17 responses in asthma, proposing an NLRP3-IL1 β -Th17 signaling axis." (PMID 36189256, 2022).